SZRD1 (SUZ RNA binding domain containing 1)
Synonyms: C1orf144; DKFZp566C0424
Tractability: PROTAC: ubiquitination databases record sites on it; its protein half-life has been measured.
Gene: Protein-coding gene on chromosome 1 (16,352,575 to 16,398,147, forward strand). Ensembl gene ENSG00000055070.
Subcellular location (Human Protein Atlas): Cytosol; Nucleoplasm
Gene Ontology:
Molecular function: protein binding
Genetic constraint (gnomAD): Loss-of-function variants: 4 observed, 12.58 expected, observed/expected ratio (o/e) 0.32, 90% interval 0.16 to 0.73. The upper end of that interval is the gene's LOEUF score, 0.73, which puts it in group 2 of 6, group 1 being the genes least tolerant of losing a copy. Missense variants: 146 observed, 177.57 expected, observed/expected ratio (o/e) 0.82, 90% interval 0.72 to 0.94. Synonymous variants: 66 observed, 72.18 expected, observed/expected ratio (o/e) 0.91, 90% interval 0.75 to 1.12.
Homologues: Orthologues: chimpanzee SZRD1 (100% identical), macaque SZRD1 (99% identical), dog SZRD1 (99% identical), guinea pig SZRD1 (99% identical), mouse Szrd1 (97% identical), rat Szrd1 (97% identical), tropical clawed frog szrd1 (84% identical), zebrafish szrd1 (68% identical).
Diseases named in the same sentence as SZRD1 in open-access papers:
SZRD1 is named in the same sentence as 6 diseases in open-access papers, as found by Europe PMC text mining. Sharing a sentence is not in itself a finding about the gene and the disease. The quoted sentences say what the papers report.
glioma (3 papers, 2021 to 2024). A benign or malignant brain and spinal cord tumor that arises from glial cells (astrocytes, oligodendrocytes, ependymal cells). "SZRD1 is considered to be a gene associated with the prognosis of glioma." (PMID 37239411, 2023). "This suggested that circ_0003945 influenced the angiogenic capacity of glioma cells by the miR-638/SZRD1 axis." (PMID 38711855, 2024). "This action effectively sequestered miR-638 from SZRD1, resulting in restrain of glioma cell proliferation." (PMID 38711855, 2024). "LINC00346 promotes cell migration, proliferation, and apoptosis by targeting ROCK1 and miR-128-3p/SZRD1 axis in glioma." (PMID 34950662, 2021).
metastatic tumors (1 paper, 2023). "Genes such as SZRD1 and ERV3-1 were upregulated in the metastatic tumors of ST survivors, as previously reported in other solid cancer types such as cervical and colorectal cancer." (PMID 37400526, 2023).
oligodendroglioma (1 paper, 2018). A well-differentiated (WHO grade II), diffusely infiltrating neuroglial tumor, typically located in the cerebral hemispheres. "Many of these candidates (e.g. ELTD1, SDHB, SEPW1, SLC17A7, SZRD1, THAP3, ZBTB17) are likely to push, whereas others (e.g. CAP1, HBXIP, KLK6, PARK7, PTAFR) might counteract oligodendroglioma development." (PMID 29890994, 2018). "Interestingly, several of these genes (e.g. ELTD1, SDHB, SEPW1, SLC17A7, SZRD1, THAP3, ZBTB17) are likely to push, whereas other genes (e.g. CAP1, HBXIP, KLK6, PARK7, PTAFR) might restrict oligodendroglioma development." (PMID 29890994, 2018).
infection (1 paper, 2023). The state of being infected such as from the introduction of a foreign agent such as serum, vaccine, antigenic substance or organism. "Comparing data collected 24 hours post-infection in each study, four phosphosites were upregulated at least two-fold in four of these studies: HSPB1/HSP27 S15, MATR3 S188, TRIM28/TIF1B/KAP1 S473, and SZRD1 S107." (PMID 37345956, 2023).
SZRD1 also shares sentences with these, for which no sentence is quoted: colorectal (1 paper); liver cancer (1).